VHL (von Hippel-Lindau tumor suppressor)
Diseases named in the same sentence as VHL in open-access papers (continued):
Sharing a sentence is not in itself a finding about the gene and the disease.
tumor (continued). "The responsible gene is VHL, a tumor suppressor located on chromosome 3p25-26, which encodes an ubiquitin ligase that is involved in the cellular response to hypoxia." (PMID 20064270, 2010). "Two different studies suggested that tumours with loss of function of VHL were more likely to be sensitive to anti-VEGF drugs, thus suggesting that both VHL and VEGF status are potentially important for predicting response to TKIs." (PMID 19755989, 2009). "We have recently demonstrated a heterogeneous expression pattern of UCHL1 mRNA and/or protein in both RCC cell lines and RCC lesions, which is associated with the RCC subtype, VHL status and with tumor progression." (PMID 19857250, 2009). "The Axl protein was highly expressed in ccRCC cells deficient in functional von Hippel-Lindau (VHL) protein, a tumor suppressor gene often inactivated in ccRCC." (PMID 19888345, 2009). "Familial renal cell carcinomas (RCC) are also among those tumor types, which are sometimes associated with VHL-inactivation." (PMID 19949549, 2009). "For example, when a tamoxifen-responsive Cre was used to inactivate the von-Hippel-Lindau (VHL) tumor suppressor during late embryonic development, the VHL-deficient embryos died six days after administration of tamoxifen due to severe liver damage." (PMID 19772675, 2009). "The von Hippel-Lindau (VHL) syndrome is an autosomal, dominant inherited disorder caused by mutations in the VHL tumor suppressor gene." (PMID 19340311, 2009). "Loss of the pVHL tumor suppressor, as occurs with Type 1 VHL mutations, is believed to promote renal tumorigenesis primarily through loss of pVHL-mediated HIF regulation." (PMID 19030229, 2008). "It is probably a combination of excessive amounts of these angiogenic factors that results in the formation of VHL-associated tumours." (PMID 18510737, 2008). "von Hippel-Lindau (VHL) disease is an autosomal dominant familial cancer syndrome caused by germline mutation or loss of the VHL tumor suppressor gene that affects approximately 1 in 36,000 individuals." (PMID 19030229, 2008). "Mutations in PTEN, PML, TSC, and VHL have been identified in tumor cells that result in the deregulation of HIF via multiple distinct mechanisms involving Akt/PI3K, mTOR and the ubiquitin pathway." (PMID 18773095, 2008). "In patients with a germline mutation in the VHL gene causing its inactivation, a tumour cell can develop when the wild type allele is lost." (PMID 17922902, 2007). "VHL disease has been shown to display a complex genotype-phenotype correlation wherein specific VHL mutations are associated with a higher risk for a subset of VHL-associated tumor types." (PMID 17598890, 2007). "In patients with at least one typical VHL-associated tumour, a clinical diagnosis of VHL disease can be made if a positive family history of a typical VHL-associated tumour exists which was the case in the reported family." (PMID 17922902, 2007). "In one hundred percent of families with a classical presentation of more than one affected family member or a classic sporadic patient with multiple VHL-related tumours, a germline mutation is found in the VHL-gene." (PMID 17922902, 2007). "It is still unclear why two apparently opposing effects are caused by one and the same missense mutation, leading to different types of tumours in VHL type 2A and 2B." (PMID 17922902, 2007). "This comparison confirms that the specific pattern of mutations identified by Brüning and Brauch is different from the pattern in the large UMD-VHL database of somatic VHL mutations in RCC tumours." (PMID 17997830, 2007). "Individuals with VHL disease harbor a germline mutation in one allele of the VHL gene and somatic inactivation of the remaining wild-type allele results in tumor development." (PMID 18047741, 2007). "Somatic mutations of the von Hippel-Lindau tumor suppressor gene are associated with the sporadic form of this tumor." (PMID 17067398, 2006).
tumor (continued). "Mutations in the von Hippel–Lindau (VHL) tumour suppressor gene are a common, early event in sporadic clear-cell renal cell carcinoma (RCC)." (PMID 16892044, 2006). "Exposure to N-nitrosamino compounds was associated with G : C → A : T transitions in the RAS gene in tumours of rodents and also with VHL mutations in rats." (PMID 16892044, 2006). "To exclude that the altered enzyme activities of the OXPHOS complex in the tumour tissue with the A3243G mutation are based on the presence of the VHL protein, we tested tumour tissues by Western blot analysis for VHL content." (PMID 16404428, 2006). "We conclude that the loss of VHL tumor suppressor function is mechanistically linked to invasive behavior through the regulation of MT1-MMP, thereby implicating MT1-MMP as a potential therapeutic target for the treatment of invasive RCC." (PMID 17140440, 2006). "Direct sequencing experiments form these sporadic tumour samples show up to 75% of these patients have biallelic loss of function mutation of VHL genes, and up to 20% exhibit expression inactivation by hypermethylation." (PMID 16465192, 2006). "Our previous data suggest that the loss of the VHL tumor suppressor, and subsequent stability of HIF-2α, leads to the induction of MT1-MMP expression in RCC." (PMID 17140440, 2006). "Contrary to what we expected, RRs were somewhat higher for VHL wild-type tumours than for VHL-mutated tumours." (PMID 16892044, 2006). "It is conceivable that genetic instability following tumor-initiating events leads to VHL mutations acquired at a later stage of tumor development." (PMID 15932632, 2005). "Tumour hypoxia and VHL gene mutations in RCC lead to accumulation of HIF-1α, this protein then leads to transcription of a number of genes which predominantly affect angiogenesis and assist in tumour expansion." (PMID 16222313, 2005). "The von Hippel-Lindau (VHL) gene is a tumor suppressor that is mutated in the majority of both hereditary and sporadic, clear-cell renal carcinomas." (PMID 15361934, 2004). "The VHL gene functions as a tumor-suppressor gene, and mutations inducing loss of function in this gene lead to impaired degradation of hypoxia-inducible factors, promoting abnormal cellular proliferation and tumor formation." (PMID 41595411, 2026). "A summary analysis was conducted on demographic information, age at first diagnosis, time to recurrence, overall survival, maximum tumor diameter, tumor locations (initial and recurrent), tumor texture, presence of VHL, surgical intervention, hemorrhage, cause of death, and embolization status." (PMID 41717405, 2026). "Moreover, HIFs are crucial in RCC, particularly in VHL-deficient tumors, where they induce reductive carboxylation (RC), a metabolic adaptation supporting tumor survival under hypoxia." (PMID 40253354, 2025). "In such cases, although these tumors are not part of any constitutional syndrome, their mere presence in a patient with a germline VHL variant could lead to the incorrect attribution of the tumor to the germline VHL." (PMID 40647474, 2025). "In cases where the familial mutation is known, targeted genetic testing can be employed to identify asymptomatic at-risk relatives and facilitate presymptomatic screening for VHL-associated neoplasms, which offers significant clinical benefits to immediate family members." (PMID 41179499, 2025). "However, restoring PGC-1α expression in VHL-deficient ccRCC cells can rescue mitochondrial function, induce oxidative stress, and significantly suppress tumor growth." (PMID 40253354, 2025). "Thus, as the earliest event in tumour formation, VHL mutation appears to induce alterations in cellular epigenetics via a number of HIF-α-dependent mechanisms." (PMID 39955388, 2025). "Based on previous studies, we hypothesize that VHL loss reshapes the ccRCC matrisome and yields a tumor-promoting microenvironment." (PMID 40753869, 2025). "The increased occurrence of various tumours is associated with VHL." (PMID 39996864, 2025).
tumor (continued). "Belzutifan, a HIF-2α inhibitor, was approved for the treatment of VHL-associated neoplasms." (PMID 40937004, 2025). "Mutations in von Hippel–Lindau (VHL) tumor suppressors are most common in ccRCC." (PMID 41476960, 2025). "In addition, specific protein abundance of the immunomodulatory proteins TIMP1 and Galectin-1 were lower in VHL-restored tumors compared to VHL-mutated tumor spheroids." (PMID 40736709, 2025). "The influence of germline genetics on tumor biology has been investigated in The Cancer Genome Atlas (TCGA), in which a decreased frequency of VHL and PBRM1 mutations was identified among patients with elevated African (AFR) ancestry, relative to European (EUR) ancestry." (PMID 40131247, 2025). "This indicates that VHL loss is necessary for tumor growth but insufficient for metastasis." (PMID 39920694, 2025). "Further research, e.g., the correlation of large genotype–phenotype maps with experimental research, may be needed to obtain reliable neoplasia risk estimates for carriers of different VHL mutations." (PMID 40202835, 2025). "Therefore, inactivation of the second allele of VHL likely marks the emergence of TICs and sets off tumor growth and subclonal evolution." (PMID 39920694, 2025). "Consequently, individuals with VHL mutations have an increased risk of developing various neoplasms." (PMID 41409896, 2025). "VHL disease results from the allelic loss or inactivation of the VHL tumor suppressor gene." (PMID 41153937, 2025). "Our results reveal that the growth of patient-derived HB cultures is strongly associated with tumor burden and recurrence in patients with VHL, suggesting that the in vitro proliferation profile may mirror disease features related to CNS-HB progression." (PMID 40427061, 2025). "By this newly established multicenter, multinational registry comprising 1,350 individuals with VHL germline mutations, we studied mutation-specific risk profiles with respect to different tumor manifestations, organs involved, performed treatments and outcomes." (PMID 40202835, 2025). "Since hypoxia can influence the expression of adhesion molecules, the mutational status of VHL may influence the physical properties of tumor spheroids." (PMID 40736709, 2025). "Furthermore, given the high expression of CA9 in RCC tumours secondary to VHL loss and constitutive HIF activation, GPR65 represents a rational therapeutic target in this disease context." (PMID 41375084, 2025). "Eighty-two to ninety-two per cent of ccRCC primary tumours harbour biallelic inactivation of the von Hippel–Lindau (VHL) tumour suppressor gene due to loss of one copy of chromosome 3p and inactivation of the second allele by mutation, deletion or hypermethylation." (PMID 39955388, 2025). "The mutation of the VHL gene is observed in patients with VHL, who may develop various neoplasms, including PanNETs." (PMID 41375037, 2025). "It is therefore reasonable to speculate that the same mechanism could induce VEGF/VEGFR2 signaling in tumor endothelial cells and thus promote angiogenesis in VHL-associated tumors." (PMID 41024941, 2025). "In contrast, EPOR expression varied based on culture duration rather than oxygen levels in the 786-O cells, indicating that EPOR expression was higher in response to reduced oxygen in tumor cells, while in tumor cells with a mutation in VHL, it depended on the length of cultivation." (PMID 40332447, 2025). "Moreover, A498 is derived from a primary tumor harboring a VHL mutation, while Caki-1 is a VHL wild type metastatic ccRCC cell line." (PMID 40975763, 2025). "Several studies have associated younger age and smaller tumor size with improved tumor control rates, which may account for the better outcomes observed in VHL patients." (PMID 40091097, 2025).
tumor (continued). "Over 70% of RCCs are clear cell RCC (ccRCC) tumours characterised by loss of function of the von Hippel-Lindau (VHL) tumour suppressor with consequent unrestrained activation of hypoxia-inducible transcription factors (HIF), which in turn leads to the over-expression of genes that drive cell growth." (PMID 41326661, 2025). "Therefore, inhibition of HIFα should be explored as a therapeutic strategy in ccRCC to improve NK cell anti-tumor efficacy against VHL-mutated tumors." (PMID 40736709, 2025). "Similarly, miR-542-5p was identified as a potential biomarker in von Hippel–Lindau (VHL)-associated ccRCC, with expression levels increasing in tumor-bearing patients and returning to baseline after nephrectomy." (PMID 40361369, 2025). "Biallelic somatic VHL inactivating variants may indicate sporadic tumors, while a monoallelic somatic inactivating variant could represent the second hit in a constitutional tumor, where the first hit is the germline VHL variant." (PMID 40647474, 2025). "Collectively, these findings proposed that MLN4924 could inhibit the tumor growth of VHL deficiency-driven ccRCC by stabilizing FBP1, providing new target and strategy for clinic treatment of ccRCC." (PMID 40419474, 2025). "3p loss, resulting in VHL loss of heterozygosity, was observed in all tumours except these three." (PMID 41241877, 2025). "The introduction of HIF-2α inhibitors, such as belzutifan, represents a paradigm shift in the medical management of VHL-associated tumors, offering a noninvasive alternative to surgery for small tumors and demonstrating significant efficacy in reducing tumor burden." (PMID 40937003, 2025). "The tumor suppressor gene VHL is the only gene implicated thus far in the pathogenesis of VHL, whereby a single inherited mutant VHL allele along with a second hit in the wild-type copy may result in tumor development." (PMID 40051608, 2025). "However, since most VHL variants are rare, it is doubtful that enough patients will ever be sequenced to reliably predict neoplasia risk for each possible VHL variant." (PMID 40202835, 2025). "Such tumor profiling could offer key insights—identifying particular somatic mutations (e.g., in VHL, FH, or BAP1) may prompt testing for the same mutation in germline DNA." (PMID 41562811, 2025). "Despite universal VHL loss of heterozygosity, tumours are clonally independent." (PMID 41241877, 2025). "Some of the patients had other VHL-associated tumours, such as haemangioblastomas and pNETs, and could therefore be investigated." (PMID 39996864, 2025). "However, local progression can still occur, especially in VHL-associated cases, highlighting the need for reliable predictive biomarkers to assess tumor behavior and guide clinical decision-making." (PMID 41382243, 2025). "Thus, inhibition of HIFα represents a valid strategy to improve NK cell anti-tumor efficacy against VHL-mutated tumors." (PMID 40736709, 2025). "In addition, a high tumor growth rate, defined as tumor diameter doubling time <500 days, and missense VHL gene variants or variants in exon 3 are considered risk factors for metastatic disease." (PMID 38893191, 2024). "The strategic activation of the AHR through a selective AHR modulator (SAhRM) may offer effective anti-tumour therapy in VHL-mutated ccRCC, reducing the need for surgical interventions." (PMID 39336758, 2024). "The VHL tumor suppressor gene contains pathogenic variants responsible for these events." (PMID 39138406, 2024). "Furthermore, combined treatment of VHL-deficient mouse tumors with autophagy inhibitors and HIF2α inhibitors suppresses tumor growth." (PMID 38360997, 2024). "Together, these findings demonstrate the importance of tumor-specific genetic alterations as a mechanism for reprogramming the immune landscape in cancer and highlight p-VHL loss–mediated CX3CL1 upregulation as a specific driver of myeloid inflammation in ccRCC." (PMID 38618956, 2024).
tumor (continued). "It is plausible that LAMP1 may be associated with tumor autophagy and VHL gene regulation; nevertheless, its specific mode of action in ccRCC remains elusive." (PMID 39669571, 2024). "In contrast, tumor-associated variants of VHL are defective in ubiquitinating AURKA." (PMID 39334449, 2024). "VHL tumorigenesis conforms to the “two-hit-model” where the first hit, that is the germline VHL mutation, exists already at birth, while the second hit, that is the somatic VHL mutation of the second allele, is the trigger for tumor development in the respective organ." (PMID 38619811, 2024). "In addition, VHL loss-mediated HIF activation leads to changes in gene expression that can significantly impact the tumor immune microenvironment (TIME) with regard to both the composition and the function of the immune cells." (PMID 39050705, 2024). "Appreciation of the effect of VHL loss on metabolism and immune infiltration in a tumor setting may provide new opportunities for targeting the TME in ccRCC." (PMID 38618956, 2024). "Moreover, we propose that this anti-tumor effect is mediated through LC3C-induced tumor autophagy and is linked to VHL." (PMID 39669571, 2024). "Furthermore, VHL inactivation also leads to the overactivation of the mTOR, which is associated with tumor progression and a poorer prognosis in ccRCC." (PMID 39092291, 2024). "VHL gene is the most frequently mutated gene in ccRCC, exerting inhibitory effects on tumor growth." (PMID 39669571, 2024). "Low expression of VHL has been found associated with tumor growth and nvasion in OSCC." (PMID 39935706, 2024). "It was also found by sequencing that SLC1A5, a glutamine transporter target of FTO, could selectively affect the survival and proliferation of tumor cells by stimulating metabolic reprogramming of VHL-deficient ccRCC cells." (PMID 39033180, 2024). "However, genetic alterations in VHL, often linked to the loss of chromosome 3p, compromise its tumor-inhibitory role." (PMID 39796121, 2024). "Since ccRCC is considered a “metabolic disease” and “VHL hyper-mutation disease”, one unexplored avenue of controlling this tumor is to target the HIF2α/LINC02609/APOL1 pathway, which may offer a veritable therapeutic window." (PMID 38263248, 2024). "Notably, ccRCC specimens with VHL deficiency exhibited elevated levels of autophagy compared to wild-type (WT) VHL-expressing tumor tissues and were associated with poorer prognosis of the patients." (PMID 38360997, 2024). "For example, VHL-deficient tumors may be more susceptible to chimeric antigen receptor T (CAR-T) therapy due to elevated levels of type I IFNs in the tumor microenvironment." (PMID 39050705, 2024). "von Hippel–Lindau (VHL) disease is a rare, autosomal dominant genetic disorder characterized by the development of multiple tumors and cysts throughout the body, resulting from germline mutations or deletions in the VHL tumor suppressor gene located on chromosome three." (PMID 39272694, 2024). "The identification of VHL gene mutations in the tumor DNA, corresponding to the donor genotype, established that the cancer in the transplanted kidney originated from an inherent genetic predisposition of the transplant’s renal parenchyma, i.e. the donor tissue, to the development of RCC." (PMID 39075385, 2024). "Attention heatmaps revealed that the Wang‐ABMIL model paid the highest attention to tumor regions in high‐TMB patients, while in VHL mutation prediction, non‐tumor regions were also assigned high attention, particularly the stromal regions infiltrated by lymphocytes." (PMID 39166457, 2024). "Associations of the VHL polymorphisms with tumor nuclear grade (G)." (PMID 38115281, 2023). "Since renal cystic lesions represent an early pathological condition that predisposes to tumor progression, both VHL role in mitotic spindle and primary cilium might be important in VHL syndrome carcinogenesis." (PMID 37477829, 2023).